GPC3 (glypican 3)
Diseases named in the same sentence as GPC3 in open-access papers (continued):
Sharing a sentence is not in itself a finding about the gene and the disease.
hepatocellular carcinoma (continued). "Killing of Huh-7 and HepG2 hepatoma cells was only observed when GPC3-CAR was reconstituted." (PMID 28123387, 2016). "In addition, in hepatocellular carcinoma, miR-219 also acts as a tumor suppressor that was found to be significantly downregulated and to be able to suppress cell proliferation by targeting glypican-3." (PMID 27663200, 2016). "Besides being a tumor marker in hepatocellular carcinomas, GPC3 also plays a role in development and progression and of HCC." (PMID 25896897, 2015). "Also, the involvement of miRNAs in postrascriptional control of GPC3 has been shown in hepatocellular carcinomas." (PMID 26517809, 2015). "It is differentially expressed in some tumor types – in hepatocellular carcinoma and melanoma, GPC3 is highly expressed; however, its expression is reduced in ovarian and breast cancer, a finding which suggests that GPC3 may be involved in tumor development." (PMID 25168166, 2014). "However, GPC3 overexpression can act as an oncogene in some tumors, such as hepatocellular carcinomas." (PMID 24570896, 2014). "However, the prognostic significance of GPC3 expression in patients with hepatocellular carcinoma (HCC) is controversial." (PMID 24548704, 2014). "The GPC3 gene is considered a potential molecular marker in hepatocellular carcinoma and may act as a tumor suppressor in the ovary." (PMID 25168166, 2014). "Furthermore, GPC3 downregulation was more significant in invasive areas, a result which further supports an inhibitory role for GPC3 in tumor progression in hepatocellular carcinomas." (PMID 25168166, 2014). "The transcription and activation of intervened GPC-3 gene by specific shRNA expression of vector mediated RNAi were successfully used to suppress the GPC-3 expression in human HepG2 cells with the viable alteration, proliferation inhibition, and apoptosis occurrence of hepatoma cells." (PMID 23192642, 2013). "Not surprisingly, they have been implicated in cancer and GPC3 is a candidate for targeted drug development against hepatocellular carcinomas." (PMID 23638093, 2013). "shRNA1 was one of the best specific plasmids for GPC-3, indicating that the highly specific and efficient shRNA1 could suppress the GPC-3 activation in hepatoma cells at the gene transcriptional or protein level." (PMID 23192642, 2013). "Glypican-3 is a rational target in hepatocellular carcinoma for antibody-based therapy." (PMID 22564378, 2012). "Unlike any other tumor antigen associated with hepatocellular carcinoma, GPC3 is a glycophosphatidylinositiol-linked membrane-associated protein with a large extracellular domain attractive for antibody-directed therapy." (PMID 22564378, 2012). "The same mechanism could also explain the preferential overexpression of GPC3 in women affected with hepatocellular carcinomas." (PMID 15083193, 2004). "Chimeric antigen receptor (CAR)-T therapy targeting GPC3 shows unsatisfactory clinical efficacy in hepatocellular carcinoma (HCC)." (PMID 41564864, 2026). "Hepatocellular carcinoma (HCC) is typically identified by markers such as arginase-1, GPC3, HepPar-1, and AFP, while cholangiocellular carcinoma (CCC) is positive for CK19 and CK8." (PMID 41515615, 2026). "BACKGROUND: Glypican-3 (GPC-3) is a promising biomarker and therapeutic target in hepatocellular carcinoma (HCC), yet its noninvasive preoperative assessment remains challenging." (PMID 41965832, 2026). "Unlike cHCC-CC, dual-phenotype hepatocellular carcinoma (DPHCC), a subtype of HCC, has typical HCC morphological features, but 15% of its cells strongly co-express HCC markers (HepPar-1, Glypican-3) and ICC markers (CK19, CK7)." (PMID 39881111, 2025). "In this study, we identified SATB1 as a key regulator of T cell exhaustion in Glypican-3 (GPC3)-targeting CAR-T cells within hepatocellular carcinoma (HCC) xenograft models." (PMID 41372119, 2025).
hepatocellular carcinoma (continued). "GPC3 is a cell surface oncofetal protein that is overexpressed in 70% of hepatocellular carcinoma (HCC) cases, and promotes tumor growth by regulating the Wnt/Frizzled signaling complex." (PMID 40433364, 2025). "GPC3, a glycoprotein present on the surface of the cell, exhibits elevated pathological expression in hepatocellular carcinoma (HCC)." (PMID 40849468, 2025). "For example, Glypican 1 (GPC1) in pancreatic ductal adenocarcinoma (PDAC) cell lines and patient blood samples, and Glypican 3 (GPC3) in hepatocellular carcinoma (HCC) patient blood samples, follow the same pattern." (PMID 40285610, 2025). "This study introduces a CD16A/GPC3 bispecific antibody (BsAb) platform as a transformative strategy for hepatocellular carcinoma (HCC) immunotherapy." (PMID 40574860, 2025). "CAR-T cell therapy for hepatocellular carcinoma (HCC) has targeted multiple antigens, with significant progress made in exploring GPC3, CD133, and CD147." (PMID 40969260, 2025). "Serum AFP is a widely used hepatocellular carcinoma (HCC) biomarker and, in the Afphi branch 1, we identified an intermediate cellular state, largely corresponding to the Dlk1+/Gpc3+ ‘hepatoblastic cluster’ (bottom)." (PMID 39112713, 2024). "NK cell therapy can also be applied to the treatment of liver tumors, with glypican-3 (GPC3) serving as a rational immunotherapeutic target for hepatocellular carcinoma (HCC)." (PMID 39682724, 2024). "While some cancer types exhibit downregulation of GPC3 expression, others, most particularly hepatocellular carcinoma (HCC), show an overexpression of GPC3." (PMID 39598037, 2024). "CAR-T cells targeting GPC3 and EGFR (CARgpc3-egfr) have been developed and demonstrated comparable proliferative capacity and cytotoxicity to CARgpc3 T cells against GPC3 + EGFR+ hepatocellular carcinoma (HCC) in vitro." (PMID 38727261, 2024). "Anti-GPC3 ScFV-modified EBPs deliver miR-26a to GPC3-expressing hepatocellular carcinoma (HCC) cells." (PMID 37608298, 2023). "Hepatocellular carcinoma (HCC) tumors are among the most common types of solid tumors, and approximately 56.3% of HCC overexpress the GPC3 protein in serum." (PMID 37665421, 2023). "The resulting H-MnO2-SRF-APT could specifically bound to glypican-3 (GPC3) receptors on the surface of hepatocellular carcinoma (HCC), rapidly undergoing subsequent degradation under decreased pH conditions in the tumor microenvironment (TME) and releasing the loaded SRF." (PMID 36457288, 2023). "A new immunotoxin based on shortened DT389 fused to humanized scFv YP7 selective to an oncophetal marker Glypican-3 (GPC3) has recently been developed and studied against hepatocellular carcinoma (HCC) cells." (PMID 36902061, 2023). "Furthermore, SF3B4 outperformed the existing diagnostic markers for hepatocellular carcinoma, namely glypican 3 (GPC3), glutamine synthetase (GS), and heat-shock protein 70 (HSP70) and demonstrated its potential as a reliable diagnostic marker for early-stage hepatocellular carcinoma." (PMID 37875914, 2023). "The present study aims at establishing a noninvasive and reliable model for the preoperative prediction of glypican 3 (GPC3)-positive hepatocellular carcinoma (HCC) based on multiparametric magnetic resonance imaging (MRI) and clinical indicators." (PMID 38023195, 2023). "GPC3 is overexpressed in various cancers, such as hepatocellular carcinoma (HCC), lung squamous cell carcinoma, and ovarian clear cell carcinoma." (PMID 35628495, 2022). "In the third decade of the 21st century, a gemcitabine-conjugated anti-glypican-3 (GPC3) aptamer has been developed for targeting hepatocellular carcinoma (HCC) cell lines and xenograft models." (PMID 36544906, 2022). "Another scFv antibody, HS20, inhibits the proliferation of hepatocellular carcinoma (HCC) cells in vitro and in vivo by binding to the HS chains of glypican-3 to block Wnt3a/β-catenin signaling, which recognizes HS structures containing IdoA2S and GlcNS6S." (PMID 36265583, 2022).
hepatocellular carcinoma (continued). "Therefore, the adenovirus vaccine of glypican-3 and interleukin 12 might become a potential way to treat hepatocellular carcinoma." (PMID 36139670, 2022). "Due to the asymptomatic nature of early hepatocellular carcinoma (HCC), HCC can only be evaluated by some early biomarkers in the patient’s body, such as serum α-fetoprotein (AFP), Glypican-3 (GPC3), and tumor-associated antigens (TAAs)." (PMID 35875077, 2022). "It was discovered that miR-4510 inversely correlated with GPC3 mRNA and protein levels in hepatocellular carcinoma (HCC) samples." (PMID 35050429, 2022). "For example, Glypican-3 (GPC3), a tumor-specific antigen, is highly expressed in hepatocellular carcinoma (HCC), hepatoblastoma, and clear-cell carcinoma of the ovary (CCCO)." (PMID 36428748, 2022). "The common multifocal nature of hepatocellular carcinoma (HCC) makes it one of the best candidates for targeted drugs and high expression of glypican-3 (GPC3) in HCC makes NIR-PIT a very appealing treatment strategy for this tumour." (PMID 33836238, 2021). "In a clinical study, 124I-codrituzumab (aka GC33), an antibody directed at Glypican 3, was evaluated in 14 patients with hepatocellular carcinoma (HCC)." (PMID 33466827, 2021). "GPC3-S-Fab could kill GPC3 positive hepatocellular carcinoma cells through natural killer cells." (PMID 34025929, 2021). "Anti-GPC3 scFv-modified exosomes effectively deliver miR-26a to GPC3-expressing hepatocellular carcinoma (HCC) cells." (PMID 34552961, 2021). "GPC3 is a membrane-bound heparan sulfate proteoglycan and overexpressed in majority of hepatocellular carcinomas (HCC), 45% of squamous cell lung cancer cases, and 19% of head and neck squamous cell cancer cases." (PMID 33791386, 2021). "In addition, this signaling axis could be a potential therapeutic target for hepatocellular carcinoma based on a monoclonal antibody recognizing the HS chains of GPC3." (PMID 32984308, 2020). "GPC3 is a tumor antigen overexpressed in hepatocellular carcinomas (HCC) with low normal tissue expression." (PMID 31544819, 2019). "On the other hand, GPC3 is expressed in hepatocellular carcinoma (HCC), melanomas, ovarian clear cell carcinoma (OCCC), lung squamous cell carcinomas, and some childhood cancers (hepatoblastomas, nephroblastomas, and yolk sac tumors)." (PMID 31024850, 2019). "An advanced SOMAmer-based assay was developed for quantification of soluble glypican-3 in hepatocellular carcinoma (HCC) patient samples using glypican-3 SOMAmer." (PMID 31861277, 2019). "Codrituzumab, a humanized monoclonal antibody against Glypican-3 (GPC3), which is expressed in hepatocellular carcinoma (HCC), was tested in a randomized phase II trial in advanced HCC patients who had failed prior systemic therapy." (PMID 30922327, 2019). "Overexpression of GPC-3 in hepatocellular carcinoma (HCC) promotes tumor growth via WNT and insulin-like growth factor (IGF) signaling." (PMID 32010611, 2019). "As a cell surface proteoglycan anchored by glycosyl-phosphatidylinositol, Glypican-3 (GPC3) is reported to be highly expressed in hepatocellular carcinoma (HCC) and to promote cell proliferation and tumorigenesis through activating Wnt/β-catenin signalling." (PMID 31160489, 2019). "GPC3 is highly expressed in 60–70% of hepatocellular carcinoma (HCC) based on immunohistochemistry (IHC) examination of surgically resected HCC tissues." (PMID 29535817, 2018). "Glypican-3 (GPC3) is a membrane proteoglycan selectively expressed by hepatocellular carcinoma (HCC) cells that is being used as a target CAR therapy." (PMID 29329556, 2018). "Codrituzumab, a monoclonal antibody targeting an oncofetal protein glypican-3 (GPC3) expressed on cell surface of hepatocellular carcinoma (HCC) induces antibody-dependent cellular cytotoxicity (ADCC) and inhibits tumor growth in preclinical studies." (PMID 29535817, 2018).
hepatocellular carcinoma (continued). "Glypican-3 (GPC3) is an oncogene, frequently upregulated in liver malignancies such as hepatocellular carcinoma (HCC) and hepatoblastoma and constitutes a potential molecular target for therapy in liver cancer." (PMID 28476031, 2017). "A study in regard to glypican-1 (GPC3), which is a new prognostic factor for early hepatocellular carcinoma (HCC), showed that epitopes selected by technical websites have the ability to bind to T2 cells." (PMID 28509875, 2017). "Among these proteins, there are some well-known features like alpha-fetoprotein (FETA) or glypican-3 (GPC3) and potential hepatocellular carcinoma (HCC) markers." (PMID 29168748, 2017). "Besides, miR-520c-3p was also a functional miRNA for proliferation inhibiting in hepatocellular carcinoma by targetting GPC3 and eIF4GII, and the hepatic impact of lead might also be a source of miR-520c-3p in plasma." (PMID 28916729, 2017). "Notably, some studies have reported GPC3 as a cell proliferation inhibitor and apoptosis inducer, therefore it may play a role in the prognosis of hepatocellular carcinoma." (PMID 27655712, 2016). "Glypican-3 (GPC3) is a cell-surface heparan sulfate proteoglycan highly expressed in hepatocellular carcinoma (HCC)." (PMID 27667400, 2016). "As in hepatocellular carcinomas, Wnt pathway may be activated by GPC3 in the positive UC cases." (PMID 25896897, 2015). "Overexpression of GPC3 has been reported in some types of cancer such as hepatocellular carcinoma (HCC), melanoma, squamous cell carcinoma of the lungs and testicular germ cell tumors." (PMID 25896897, 2015). "The glypican-3 (GPC3) is a hepatocellular-specific cell surface proteoglycan overexpressed in most hepatocellular carcinomas (HCC)." (PMID 24991539, 2014). "We also revealed that GPC3 is an ideal target for anticancer immunotherapy since it is specifically overexpressed in hepatocellular carcinoma (HCC)." (PMID 24842630, 2014). "We conducted a clinical trial using the glypican-3 (GPC3) peptide vaccine in advanced hepatocellular carcinoma (HCC) patients." (PMID 23143746, 2013). "Glypican 3 (GPC-3) is an oncofoetal protein that is expressed in most hepatocellular carcinomas (HCC)." (PMID 20465843, 2010). "GPC3 has also been linked to various sporadic tumors, particularly hepatocellular carcinoma, for which it has been shown to be a useful diagnostic marker helpful in differentiating hepatocellular carcinoma from non-neoplastic liver disease." (PMID 20868507, 2010). "Background/Objectives: Glypican-3 (GPC3), a membrane-bound heparan sulfate proteoglycan, has been identified as a promising target for both the diagnosis and treatment of hepatocellular carcinoma (HCC)." (PMID 41897583, 2026). "In this case, the positive expression of HepPar-1, AFP, glypican-3 and CK7/CK19 is in agreement with the features of hepatocellular carcinoma." (PMID 39931054, 2025). "Pathological examination: Hepatocellular carcinoma (immunohistochemistry: CK19+, AFP+, Hepatocyte+, Glypican-3+)." (PMID 41431067, 2025). "For example, research has demonstrated that elevated levels of specific proteins, including Glypican-3 (GPC3), in circulating EVs are correlated with hepatocellular carcinoma, establishing them as reliable indicators for early detection." (PMID 41278193, 2025). "Glypican-3 (GPC3), which is highly expressed in both hepatoblastoma and hepatocellular carcinoma, has emerged as a promising immunotherapeutic target." (PMID 40684183, 2025). "For instance, glypican-3 (GPC3) enhances Wnt/β-catenin signaling by concentrating Wnt ligands near FZD receptors, a mechanism frequently observed in hepatocellular carcinoma." (PMID 40376615, 2025). "For example, in 2021, Vδ1 T cells were engineered using a glypican-3–specific CAR and soluble IL-15 to combat hepatocellular carcinoma." (PMID 40148988, 2025).
hepatocellular carcinoma (continued). "Glypican 3 (GPC-3), a member of the heparan sulfate proteoglycan family, is another oncofetal protein found elevated in hepatocellular carcinoma cells and serum small extracellular vesicles." (PMID 40269686, 2025). "Additionally, CStone Pharmaceuticals’ GPC3-targeted CAR-T therapy has yielded notable outcomes in advanced hepatocellular carcinoma (HCC), with two patients remaining tumor-free for over seven years." (PMID 40066440, 2025). "Coexpressing IL-15 and IL-21 in GPC3 CAR further increased T-cell viability and antitumor ability in a hepatocellular carcinoma model (NCT02932956, NCT02905188)." (PMID 40481182, 2025). "Anti-GPC-3 chimeric antigen receptor (CAR) T-cells, combined with soluble IL-15, have shown significant efficacy in preclinical mouse models of hepatocellular carcinoma (HCC), highlighting GPC-3’s therapeutic potential." (PMID 39404428, 2024). "There are many types of CAR-T cells, among which GPC3 CAR-T cells, CD133 CAR-T cells, c-Met CAR-T cells, NKG2D CAR-T cells, and other CAR-T cells effectively treat hepatocellular carcinoma." (PMID 39136031, 2024). "STK-009 administration enhanced the anti-tumor efficacy of anti-glypican 3 (GPC3) CAR-T cells (SYNCAR-002) in highly aggressive subcutaneous and intraperitoneal hepatocellular carcinoma models." (PMID 39114660, 2024). "Addition of CXCR2 expression by GPC3-targeted CAR T cells has previously been shown to increase homing and produce greater in vivo anti-tumoral effects in a mouse xenograft model of hepatocellular carcinoma (HCC)." (PMID 38554158, 2024). "Importantly, Apt-USPIO could obviously target GPC3 on hepatocellular carcinoma in xenograft mice." (PMID 38191388, 2024). "NTA concentration quantification of GPC3- and AFP-positive EVs in hepatocellular carcinoma patient serum were compared to that from healthy controls, indicating a positive correlation of serum concentration of GPC3-positive EVs with tumor size." (PMID 39407601, 2024). "In hepatocellular carcinoma (HCC), glypican-3 knockdown reduces the lactylation of c-myc and further reduces the protein stability and expression of c-myc, thereby inhibiting the progression of liver cancer." (PMID 38200523, 2024). "Moreover, in this study treatment with a LIN28 inhibitor, C1632, significantly augmented the tumor-killing activity of the GPC3-CAR T cells against hepatocellular carcinoma cell (HCC) lines in vitro and in vivo through inhibition of PD-L1 and IDO in the tumor." (PMID 39478867, 2024). "A hepatocellular carcinoma vaccine that combines the XCL1 chemokine and glypican-3 (GPC3) added to the positive effect of anti-PD-1 therapy." (PMID 38928238, 2024). "In hepatocellular carcinoma (HCC), a CAR-T was developed against a potential antigen target, i.e., glypican-3 (GPC3)." (PMID 36765623, 2023). "The expression of hepatocellular carcinoma markers, including AFP, Arginase-1, Glypican-3 (GPC-3), SALL4, and Hep-1, provides valuable insights into the correlation with hepatocytes." (PMID 37950062, 2023). "However, a recent study of IL-15-expressing GPC3 CAR-T cells reported that infusion of those CAR-T cells into a patient with hepatocellular carcinoma (HCC) led to grade 4 cytokine release syndrome (CRS), which could be controlled by administration of rimiducid to trigger apoptosis of CAR-T cells." (PMID 37564658, 2023). "Notably, GPC3 is overexpressed in hepatocellular carcinoma (HCC) and is a biomarker for HCC diagnosis." (PMID 37366982, 2023). "A phase I clinical trial was conducted in patients with glypican-3 (GPC3) and mesothelin (MSLN)-positive advanced hepatocellular carcinoma (HCC), pancreatic cancer (PC), and ovarian cancer (OC)." (PMID 37190280, 2023). "Glypican-3 (GPC3) was reported to mediate the CSC properties like self-renewal, cell cycle progression, and tumor formation via autophagy induction in hepatocellular carcinoma, implicating it as a novel liver CSC marker." (PMID 36910604, 2023).